IL10 (interleukin 10)
Diseases named in the same sentence as IL10 in open-access papers (continued):
Sharing a sentence is not in itself a finding about the gene and the disease.
Allergy (continued). "IL-10 has a potent immunosuppressive function by inhibiting the production of pro-inflammatory chemokines and cytokines and establishing immune balance in response to a pathogen, autoimmune disease, and allergy." (PMID 33123017, 2020). "In this mouse model of allergy, IL-10 is a promoter of allergic reactions." (PMID 32369940, 2020). "It is believed that enhancing IL-10 activity in allergic diseases such as asthma could be beneficial to pathology, and in CVD there is evidence that also supports this hypothesis." (PMID 32194407, 2020). "Importantly, mice administered with IL-10-treated BM-DCs in a tolerance-inducing protocol, exhibited reduced allergic disease manifestations and Th2 responses that remained suppressed for up to 8 months." (PMID 33114551, 2020). "Given that IL-10 has been reported to cooperate with IL-4 in inducing B cell production of IgG4, and that the latter correlates with allergy desensitization and tolerance, we asked whether CD25+ TF cells could also regulate IgG4 responses." (PMID 31209070, 2019). "Therefore, the presence of exhausted-like Tigit+IL-10+ ILC2s is likely to reduce acute deterioration of chronic allergy." (PMID 30893794, 2019). "The balance between pro-inflammatory CD4+ Th2 cells and regulatory T cells, including CD4+Foxp3+ regulatory T cells (Treg) and CD4+Foxp3-, interleukin-10 (IL-10)-producing Type one regulatory T cells (Tr1) cells, is a significant determinant in the development of allergic disease." (PMID 31603425, 2019). "The inverse correlation between IL-10 and allergic diseases and asthma were observed." (PMID 30813365, 2019). "Besides these strategies, several other factors have been described to promote the differentiation of IL-10-producing DC subsets in the context of allergies." (PMID 29616018, 2018). "Furthermore, numerous clinical trials have reported that specific treatments for allergies increase IL-10 levels." (PMID 30013991, 2018). "Further study of the cells and mechanisms involved in IL-10’s downregulation of IgE class switch and production and of the direct enhancement of IgG4 production will lead to better understanding of and treatment modalities for allergic diseases." (PMID 31026808, 2018). "Because of its broadly anti-inflammatory effects, IL-10 is a highly interesting molecule for the treatment of allergic diseases, where affected patients mount exaggerated, immunoglobulin E (IgE)- and Th2-mediated immune responses against otherwise harmless environmental antigens." (PMID 29616018, 2018). "As in allergy, the depletion of Tregs is observed and the results of allergen-specific immunotherapy could be measured by an increase in the population of IL-10+ regulatory cells." (PMID 28470464, 2017). "However, the cellular source of IFNγ and its role, as well as the exact role of IL-10 in allergy-suppression by TLA still remains to be investigated." (PMID 29123241, 2017). "In addition, to evaluate the anti-inflammatory activity in allergic reactions induced by OA, we measured IL-10 in the BALF of the animals." (PMID 28649241, 2017). "We identified seven cytokines from previous glioma or allergy literature (IL4, IL13, IL5, IL6, IL10, IFNG and TGFB2) to determine whether, they were associated with glioma before diagnosis." (PMID 26352148, 2015). "IL-10 is a key regulator of human immune responses and possesses many immunosuppressive functions that protect the host from abnormally strong inflammation and subsequent tissue damage playing a protective role in allergic disease." (PMID 26473365, 2015). "Because of its immunosuppressive and anti-inflammatory properties, it has been suggested that IL-10 and regulatory T cells could be of therapeutic benefit in the treatment of allergic diseases such as atopic asthma." (PMID 25430775, 2015). "We conclude that GSK3 inhibition leads to a stable upregulation of IL-10 in Th1 and Th2 cells, which may be beneficial in the development of new therapies for autoimmune and allergic diseases." (PMID 25627813, 2015).
Allergy (continued). "The involvement of Th2 cells both helps to explain the joint involvement of IgE-producing B cells (via IL-4 and IL-13), mast cells (via IL-4 and IL-10), and eosinophils (via IL-5) in the allergic inflammatory process and accounts for the other pathophysiologic features of allergies." (PMID 24707309, 2014). "The present results showed an important association between SNPs in cytokine genes and susceptibility to or protection from allergy to dust mites in IL1A at position −889, IL4RA at position +1902, IL2 at positions −330 and +166, IL4 at position −590, and IL10 at position −592." (PMID 25238536, 2014). "The involvement of Th2 cells both helps to explain the joint involvement of IgE-producing B cells (via IL-4 and IL-13), mast cells (via IL-4 and IL-10) and eosinophils (via IL-5) in the allergic inflammatory process and accounts for the other pathophysiologic features of allergy." (PMID 24624888, 2014). "It is tempting to speculate that the immunoregulatory properties of BCG in autoimmunity and allergies are related to IL-10 production and are consequently lost in undernourished individuals." (PMID 22567029, 2012). "polygyrus infected mice could still protect from allergy to these antigens, suggesting that IL-10 independent mechanisms can confer protection from allergy." (PMID 23053394, 2012). "IL-10 is a key regulator of allergic diseases, not only because it downregulates the Th2 cell-derived cytokines IL-4 and IL-5, but also because it directly inhibits the IgE-induced degranulation of mast cells, which leads to a reduced secretion of the inflammatory mediator histamine." (PMID 23346203, 2012). "Because this probiotic strain is frequently used in the management of allergic diseases or gastroenteritis, it is hypothesized that it promotes mucosal tolerance mediated through IL-10." (PMID 22681958, 2012). "Although we have focused on TH1 responses, the same approach could also be applied using different reporters to the sensitive detection of antigen-specific TH2 cells involved in allergy (e.g. IL-4 or 5 induced genes) and IL-10 or IL-17 secreting T cells." (PMID 21853018, 2011). "Children sensitive to allergy showed 15% more IL-16, 32% more IL-13 and similar levels of IL-10." (PMID 20534153, 2010). "Thus, the higher levels of IL-4, IL-10 and IL-33 found in DK may reflect the higher prevalence of allergies typically seen in high-income countries (HIC) compared to low- and middle-income countries (LMIC)." (PMID 40338935, 2025). "As the results, we found that SAE immunotherapy reduced systemic allergy symptom scores, serum IL-4 levels, IL-4 and FcεR1α mRNA relative expression, and mast cell degranulation in ileum tissue in allergic mice while increasing Foxp3 and IL-10 mRNA relative expression." (PMID 39729447, 2024). "In addition, the role of IL‐10 is far more complex and may affect epithelial function and be involved in allergies." (PMID 39644500, 2024). "Similarly, during the allergy season, the levels of IL-4 and IL-10 decrease in nasal fluid." (PMID 37692890, 2023). "Although allergic diseases and helminth infections share several mechanisms of type 2 immunity, including the increase of total and specific IgE, helminths are also able to modulate the inflammation through regulatory cytokines (i.e., IL-10 and TGF-β) leading to the production of IgG4 antibodies." (PMID 37887050, 2023). "Furthermore, the IL-17A, IL-23, IFN-, IL-4, and IL-10 serum levels were also compared according to gender, antihistamine receiving, nose picking, bleeding of the gums, smoking, familial history of epistaxis, and clinical presentations similar to allergies." (PMID 35145935, 2022). "However, studies have also reported that IL-10 is essential for inducing allergy symptoms." (PMID 37430973, 2022).
Allergy (continued). "Thus, it is likely that M. vaccae NCTC 11659 may restore adequate levels of those cytokines, a hypothesis that is also supported by studies in mice showing increased numbers of Tregs secreting IL-10 and TGFβ1 in a model of allergy." (PMID 34884743, 2021). "Additionally, IL-10 has been shown to be critical for Th2 responses in a murine allergy model." (PMID 31429774, 2019). "Therefore, LAB that induce the production of IL-12, IFN-γ, and IL-10 may exert preventive and therapeutic effects for treating allergies." (PMID 31167991, 2019). "In line with this, DC-derived autocrine IL-10 secretion was shown to suppress high-affinity IgE receptor Fc epsilon receptor I-dependent pro-inflammatory responses, suggesting that increased IL-10 production by DCs during allergy immunotherapy may reduce inflammatory responses to the allergen." (PMID 29616018, 2018). "Such increases in allergic diseases may be related to increased IL-5 and IL-10 levels." (PMID 27918476, 2016). "Notably, IL-10-dependent immunoregulation induced by peptide immunotherapy was observed in other murine models of allergic diseases, such as in birch pollen-, house dust mite- and cat dander- mediated allergies." (PMID 27642756, 2016). "Bovine IL-10 present in dairy products may thus potentially contribute to the prevention of necrotizing enterocolitis and allergy, enhance mucosal tolerance induction and decrease intestinal inflammation and may therefore be applicable in infant foods and in immunomodulatory diets." (PMID 21464967, 2011). "Likewise, application of bovine IL-10 or TFG-β in infant nutrition over a long period may contribute to the prevention of allergy." (PMID 21464967, 2011). "IL-10 may also promote airway hyperresponsiveness and eosinophilia in models of allergy." (PMID 21197090, 2010). "Finally, IL-10 can be produced by T cells and is able to diminish PMN influx by inhibition of expression of proinflammatory chemokines, NF-κB (via I kappa kinase), and TNF, as well as modulate cells and effector functions associated with an allergic response." (PMID 16026622, 2005). "The results showed that Lp synergistic FOS significantly decreased clinical allergy scores, inhibited specific antibodies (IgE, IgG, and IgG1), IL-4, IL-6, and IL-17A levels, and increased IFN-γ and IL-10 levels." (PMID 39796399, 2025). "Collectively, these findings indicate that IL-10 not only exerts direct anti-inflammatory effects in AR but may also modulate metabolic pathways to mitigate disease progression, highlighting IL-10-mediated metabolic regulation as a potential therapeutic target in allergic diseases." (PMID 40570726, 2025). "IL-10 suppresses the proliferation of TH1-type responses by acting on DCs and macrophages, but it has the opposite effect on TH2 cells and allergic reactions." (PMID 40166075, 2025). "The results suggest that the body weight and thymus index returned to normal levels; allergy scores, serum OVA-sIgE, IL-4, IL-5, and IL-10 expression decreased; and IFN-γ and IL-2 increased significantly in the ZW3 group compared with the allergy group." (PMID 39796306, 2024). "At steady state (OVA feeding), ∼50% of incoming Tregs were Il10 high pTregs, whereas this dropped to ∼20% in either OVA tolerance or allergy conditions." (PMID 37191720, 2023). "A significantly smaller CD8+ iNKT cell population producing IFN-γ, IL-4, IL-5, and IL-10 in peanut-allergic adults was identified after exposure to DCs loaded with peanut oil, suggesting that despite a higher overall iNKT cell population, certain iNKT cell responses may be reduced in allergy." (PMID 38022648, 2023). "In particular, ILC2s are involved in allergic diseases of the respiratory system as well as TH2 cells and promote the expansion of IL10-producing T-regs." (PMID 38027278, 2023).
Allergy (continued). "IL-10 and IFN-γ cytokines have been shown to inhibit effector T cell proliferation in allergic diseases, and both can be produced by Tregs Consequently, IL-10 and IFN-γ levels were measured in culture supernatants using a suppression assay." (PMID 38106504, 2023). "Anti-inflammatory cytokines (IL-10 and TGF-β) are secreted by Tregs, which ultimately reduce the amount of pulmonary eosinophil infiltration as well as the production of allergy-specific Th2 cytokines and Ig." (PMID 36556359, 2022). "Tregs secrete regulatory cytokines such as and IL-10 and TGF-β, which reduce pulmonary eosinophil infiltration, allergy-specific Th2 cytokines (IL-4, IL-5, and IL-13), allergy specific IgG1 and IgE production, allergic rhinitis symptoms, and AHR." (PMID 36556359, 2022). "The cytokine release of IL-4, IL-10, and IFN-γ was then determined via quantitative equine capture ELISA (R&D systems, Minneapolis, MN, USA) in order to detect an allergy-mediated Th2 immune response (IL-4) and/or a proinflammatory Th1 response (IFN-γ)." (PMID 36009677, 2022). "To evaluate the clinical signs of allergy to dietary BSFL and FO, we investigated the skin status (TEWL and contents of moisture and oil), fecal score, and immune-related parameters (IgG, IL-10, and TNF-α) in serum." (PMID 34944285, 2021). "We observed that ROS induction promoted IL-10 secretion and IL-10+IFN-γ+ Treg expansion, which ameliorated the allergic reaction." (PMID 33995359, 2021). "It is found that exogenous LL-37 decreased TNF and IL17A expression while inducing anti-inflammatory IL-10 and TGF-β production in dendritic cells in allergy and inhibit LMW-hyaluronan-induced cytokine release in skin fibroblast." (PMID 31260471, 2019). "The results showed that IFN-γ level was significantly higher (p < 0.05), while IL-4 and IL-10 levels were significantly lower in the control and FOS groups compared with the allergy group (p < 0.05)." (PMID 30524396, 2018). "IL-10 and TGF-β are the two chief regulatory cytokines and have been proven to play crucial roles in controlling allergy and establishing tolerance to environmental antigens." (PMID 30475891, 2018). "Consistent with these lines of evidence, the production of IL-10 by B10 cells was recently shown to be dependent on the BCR signaling pathway, and its function can inhibit murine allergies and autoimmunity." (PMID 28428801, 2017). "Increases in Il-10, another TH2 cytokine that has been shown to have a role in allergic disease, were also observed following the extended DDAB application at high concentration." (PMID 29124973, 2017). "Children who developed allergies in the first 3 years of life had lower numbers of CD4+CD25+FOXP3+ T cells and reduced FOXP3 expression and IL-10 production as newborns (P < 0.05)." (PMID 27646403, 2016). "Tregs secrete anti-inflammatory cytokines (IL-10, TGF-β), which ultimately lead to decrease of lung eosinophil infiltration, as well as allergy-specific Th2 cytokines and Ig production." (PMID 25246732, 2014). "The multiple linear regression analysis showed that after Derp 1 specific stimulation, allergy (R + AR) correlated positively with percentages of ICOS, IL-13 and IL-4-expressing T cells and negatively with CTLA-4 and IL-10-expressing T cells." (PMID 21356099, 2011). "Increased ratio of proinflammatory cytokines (IL-17, TSLP, and IL-6) versus regulatory cytokines (IL-10 and TGF-β) in severe allergic diseases would activate further the balance shift and form a positive feedback loop in chronic inflammation." (PMID 23283296, 2008). "Also IL10 seems to be important where production in circulating T cells from atopic asthmatics is maximally stimulated; allergen specific IL10 producing T regulatory cells can inhibit allergen specific effector cells and represent an important line of defense in the allergic reaction." (PMID 16600026, 2006).
Allergy (continued). "For instance, IL4, IL13 IL10, and IFN-γ, which are anti-inflammatory/regulatory cytokines, can modulate inflammatory processes like allergies and intestinal inflammatory diseases by regulating the immune response of the T helper 2 cells (Th2) and the T helper 1 responses (Th1)." (PMID 39891859, 2025). "If chronic HCV infection indeed promotes a tolerogenic immune state via IL-10 and TLR7 pathways, therapeutic strategies aimed at enhancing such regulatory circuits could be explored in allergic disease." (PMID 41465112, 2025). "In support of this, healthy beekeepers without allergic disease demonstrate activation of IL-10–secreting regulatory T cells." (PMID 41462820, 2025). "With regard to regulatory cytokines, IL-10 and TGF-ß are found mainly in the allergen-specific Treg cell population, and there is strong evidence that peripheral T-cell regulation has a crucial role in the control of allergies." (PMID 38067164, 2023). "In humans, IL-10+ILC2 were rarer in individuals with grass pollen and house dust mite allergies compared to healthy individuals, indicating that these cells could facilitate tolerance to allergens." (PMID 37947634, 2023). "On the basis of murine observations that maternal IgG inhibited offspring allergy, some translational approaches have revealed that peripheral B cells can be modulated to acquire regulatory functions by secreting IL-10 in response to IgG from nonatopic donors." (PMID 35743310, 2022). "Some studies have indicated that the levels of IL-4 and effector T cells in patients with allergic diseases are significantly higher compared to patients without allergic diseases, while the levels of IL-10 and Treg are decreased." (PMID 36045965, 2022). "An important issue that needs to be emphasized considering in vitro tests is the fact that cytokines are determined in various conditions and various diseases; however, only certain cytokines (i.e., TNF-α, IL-2, IL-4, IL-5, IL-6, IL-10, IL-13, and IFN-γ) are important in allergic reactions." (PMID 36590449, 2022). "This study suggests that butyrate may improve AR by upregulating Tregs in colon mucosa and increasing serum IL-10 and TGF-β1 levels to exert immune tolerance and inhibit allergic reactions." (PMID 36439824, 2022). "The cytokine environment in the BAL showed a bias toward increased IL-10 production, suggesting for the first time an involvement of Tregs following i.g.-administered M. vaccae NCTC 11659, with potentially beneficial consequences for the treatment of allergy." (PMID 34884743, 2021). "Of note, cells producing both IL-4 and IL-10, but not IL-4+ IL-10− Th cells, were lost in this allergy model, in keeping with increased pathology." (PMID 32117317, 2020). "As mentioned in the introduction, plasma IDO activity and IL-10 levels were shown to be higher in allergy patients without clinical symptoms than in symptomatic allergy patients and healthy individuals." (PMID 32834826, 2020). "In addition, in the asthmatic allergy model, it was shown that TSLP directly and selectively impairs IL-10 production of Treg and inhibits their suppressive activity." (PMID 32435245, 2020). "Some studies have shown that probiotics could reduce IgE level in the blood and reduce the incidence of allergies through increasing IFN-γ and IL-10." (PMID 31719960, 2019). "The Tigit+IL-10+ ILC2s with low reactivity can be found only in the bronchoalveolar space, but not in the lung during severe subacute allergy induced by high doses of papain." (PMID 30893794, 2019). "In the present study, mRNA levels of IL-10 was higher in allergy mouse group than that in the negative control group." (PMID 30814581, 2019). "Additionally, the gestational cytokine environment appears to differ during allergy-protective acute (pre-patent) and chronic maternal phases of schistosomiasis (IFN-γ and IL-10-dominated responses, respectively)." (PMID 30619318, 2018).